SREBF1 (sterol regulatory element binding transcription factor 1)
Diseases named in the same sentence as SREBF1 in open-access papers (continued):
Sharing a sentence is not in itself a finding about the gene and the disease.
Obesity (350 papers, 2006 to 2026). Accumulation of substantial excess body fat. "In the blood-based integrative analyses, this site was linked to SREBF1 (β=−0.004, pfdr=8.3 × 10−5), which encodes a TF central to lipid homeostasis and biosynthesis and whose expression is decreased in obesity and type 2 diabetes." (PMID 41057690, 2026). "In a study focusing on Chinese children, distinct genetic variants of SREBF1 exhibited differential responses to cholesterol, thereby contributing to varying risks of obesity and obesity-related metabolic traits." (PMID 40702573, 2025). "Many genes on this list are involved in different processes associated with T2DM development, such as obesity (SREBF1 and H6PD), inflammation (TGFB1), and insulin resistance (RPTOR and AKT1)." (PMID 39273245, 2024). "Multiple of the top DMPs were annotated to genes with relevant functions for diabetes including SREBF1, associated with obesity, type 2 diabetes and insulin sensitivity; ABCG1, involved in cholesterol and phospholipids transport; and HDAC1, of the HDAC family." (PMID 36529747, 2022). "The SREBF1 gene is associated with obesity, type 2 diabetes and insulin sensitivity, and the gene ABCG1 is involved in cholesterol and phospholipids transport." (PMID 36529747, 2022). "In this example, 16 DMSs in genes, such as CPT1A, ABCG1, SLC7A11, RNF145, and SREBF1 were reported to be associated with obesity-related phenotypes." (PMID 35047011, 2021). "The genetic IV analyses prioritize the SREBF1 locus for future functional studies to further define the causal relation with adiposity, insulin resistance, obesity-related dyslipidemia, and coronary artery disease." (PMID 28095459, 2017). "Obesity and diabetes have been established as known risk factors of EC, while SREBF-1 gene polymorphisms have also been found to be associated with obesity and type II diabetes." (PMID 24614076, 2014). "Study of miR-33−/−Srebf1+/− mice clearly showed that enhanced expression of SREBP-1 caused obesity and fatty liver in miR-33−/− mice." (PMID 24300912, 2013). "Nevertheless, all these obesity-associated pathways were annotated from only 3 genes, namely ABCG1, CPT1A, and SREBF1." (PMID 40702573, 2025). "SREBF1 has been demonstrated to play a pivotal role in the development of obesity and metabolic syndrome." (PMID 40702573, 2025). "At present, it is identified that the increased expression levels of adipogenic-specific genes including SREBF1, FAS, ACC and SCD1 are associated with HFD-induced obesity." (PMID 38504370, 2024). "The dysregulation on this pathway alters PGC-1α (Peroxisome Proliferator-Activated Receptor Gamma Coactivator 1-alpha), SREBP-1c (Sterol Regulatory Element-Binding Transcription Factor 1), and NF-κB, enhancing obesity." (PMID 33123088, 2020). "SREBF1 was shown to regulate carbohydrate metabolism and synthesis in an animal model of obesity and T2D." (PMID 26823690, 2016). "A previous study detected 19 polymorphisms in SREBF-1 and demonstrated the association between SREBF-1 polymorphisms and obesity as well as type II diabetes." (PMID 24614076, 2014). "Furthermore, numerous studies have identified the epigenetic modifications on various robust genes like the FTO, NBPF3, and SREBF1 were related to obesity, suggesting the regulatory role of genetic factors in obesity-associated methylation changes." (PMID 40702573, 2025). "As a master transcriptional regulator of lipid metabolism and cholesterol biosynthesis, SREBF1 may be modulated through obesity-altered metabolic pathways, potentially mediating weight-dependent cancer progression." (PMID 40668814, 2025). "Previous studies in obese adults and normal mice have shown that consumption of high fat diet could affects GIPR and SREBF1 genes expression signalling that prevent obesity and improve insulin sensitivity." (PMID 40347281, 2025).
Obesity (continued). "However, this pathway becomes inhibited by hyperinsulinaemia induced by obesity, leading to increased lipogenesis through the sterol regulatory element‐binding transcription factor 1 (SREBP1c)." (PMID 39207362, 2024). "For example, obesity has been linked with methylation changes in genes involved in lipid metabolism (ABCG1, SREBF1, and NOD2), which may explain the comorbidities noted in obesity." (PMID 36656735, 2023). "However, OT intervention exerted a preventive effect on obesity possibly by regulating β-oxidation of fatty acid (Ppara and Pgc1a), cholesterol removal (Lxra), lipolysis (Srebf1 and Hsl), and low-grade inflammation (Il-6 and Il-1b)." (PMID 35967777, 2022). "Major downstream pathways of AMPK, such as the sterol regulatory element-binding transcription factor 1 (SREBF1, also known as SREBP1) pathway related to lipogenesis and the mechanistic target of rapamycin (mTOR) pathway, whose activation contributes to obesity, were downregulated by GTE." (PMID 31500159, 2019). "SREBF1 is a transcriptional factor related to lipid synthesis, regulating the homeostasis of cholesterol and fatty acids, and it was identified as a potential tool for treating obesity-related metabolic syndrome since SREBF1 inhibition can suppress lipogenesis." (PMID 38003013, 2023). "Hence, the miR-122/VDR/SREBF1 axis might be upregulated by Exo-AT, promoting lipogenesis and speeding the development and progression of obesity, since miR-122 contributes to adipogenesis by inhibiting VDR and activating the SREBF1 signaling pathway." (PMID 38003013, 2023). "Therefore, dietary fat-induced down-regulation of Abca1 and up-regulation of Scd1 and Srebf1 might contribute to development of obesity and/or insulin resistance." (PMID 18457598, 2008). "Obesity indirectly regulates de novo lipogenesis of fatty acids by controlling downstream AKT1 and SREBF1 through IL6." (PMID 39928768, 2025). "Furthermore, the suppressed expression of inflammatory factors, regulatory expression of catabolism genes including Srebf1, Pgc1a, Lxra, Hsl, Leptin, and Ppara; the modulatory effect of microbial diversity; and richness were responsible for the preventive mechanisms against obesity of OT." (PMID 35967777, 2022). "In essence, our findings imply that the identified epigenetic loci at CPT1A, SREBF1, and ABCG1 can link obesity to hyperlipidemia (high TG) and elevated postprandial TG response, and then to the risk of CVD." (PMID 27777315, 2016). "miR-122 is enriched in adipose tissue–derived exosomes; it can target VDR and interact with the BS1 region of the sterol regulatory element-binding transcription factor 1 (SREBF1) promoter to suppress VDR and SREBF1 expression, thus leading to the pathogenesis of obesity." (PMID 36864020, 2023). "Similarly, in animal models of high-fat diet-induced obesity, switching to a balanced chow diet restored standard methylation patterns of LEP promoters, SREBF1 (sterol regulatory element-binding transcription factor 1), PGC1A, and FASN." (PMID 35163268, 2022). "As Yarrow SFE diminishes the expression of SREBF1 in pancreatic cancer cells and in a xenograph mouse model, we wanted to analyze the impact of Yarrow SFE in C57/Bl6 mice under standard diet (SD) or high-fat diet (HFD)-induced obesity." (PMID 31888081, 2019). "Some Asian red algae have already been reported to have anti-obesity effects; for example, the extracts of Plocarmium telfaireaes (PTE), a Korean red alga, inhibited adipogenesis of mouse pre-adipocyes with downregulation of Pparg, Cebpa, and Srebf1." (PMID 30279329, 2018). "Additionally, SREBF1 interacts with other genes and metabolic pathways, such as promoting adipogenesis through the regulation of the VDR/SREBF1 axis, consequently influencing the progression of obesity." (PMID 40702573, 2025).
Obesity (continued). "The most significant findings included hypermethylation of CpG cg11024682, located within the body of the SREBF1 gene, and hypomethylation of cg13424229, situated in a GATA binding factor 1 cluster within the promoter region of CPA3, in patients with early-onset obesity." (PMID 40869388, 2025). "Also, while LXR DKO mice are resistant to diet-induced obesity and hepatic accumulation of triglycerides, Srebf1 KO mice are not." (PMID 39241209, 2024). "Pparg and Srebf1 also activated genes involved in carbohydrate metabolism, including those in the glycogen, TCA cycle, and glycolysis and gluconeogenesis pathways, in the ob/ob mice, suggesting that these DRTFs coordinate altered lipid and carbohydrate metabolism in obesity." (PMID 33748705, 2021). "Increased hepatic Srebf1 expression in these models, which accords with hepatic Srebf1 expression patterns in fat fed mice and in obese Lepob/ob mice, may therefore represent a universal adaptive response to HFD or obesity independent of NAFLD susceptibility." (PMID 24324835, 2013).
Insulin resistance (296 papers, 2008 to 2026). Increased resistance towards insulin, that is, diminished effectiveness of insulin in reducing blood glucose levels. "SREBP-1a and SREBP-1c are encoded by SREBF1 and have been linked to type 2 diabetes, glycemia, and insulin resistance in humans." (PMID 40347281, 2025). "Another study found that differentially methylated CpG sites at well-established lipid-associated genes ABCG1 and SREBF1 were also associated with insulin resistance and BMI in blood, liver, and adipose tissues." (PMID 40176173, 2025). "Mutations in SREBF1 sequence are associated with an increase in type 2 diabetes risk and insulin resistance." (PMID 35757772, 2022). "The SREBF1 was elevated 2.4 fold in HFD fed rats implicating the cause of insulin resistance and hepatosteatosis as confirmed by histology." (PMID 24638096, 2014). "SNPs within the SREBF1 gene have been frequently associated with type 2 diabetes or insulin resistance." (PMID 25270430, 2014). "Srebf1 overexpression is strongly associated with insulin resistance, diabetes, and NAFLD." (PMID 39537943, 2024). "Sterol regulatory element-binding transcription factor 1, involved in insulin resistance and insulin signaling, was elevated." (PMID 40438215, 2025). "SREBP1c, one of the transcription factors of SREBF1, exerts a pivotal role in insulin resistance and insulin signaling pathways." (PMID 39130628, 2024). "The effects of diet composition on hepatic insulin resistance were evaluated by examining responses of insulin-regulated genes, many of which have roles in hepatic lipogenesis (Srebf1, Insig2, Acaca, Fasn, Scd1, and Gck)." (PMID 31061673, 2018). "In mice with diet-induced insulin resistance, inhibition of SREBF1 attenuates accelerated atherosclerosis, supporting a link to atherosclerosis and coronary artery disease." (PMID 28095459, 2017). "In summary, our data suggest epigenetic regulation of the Srebf1 network as an integral mechanism by which DR protects organisms against age-related steatosis and hepatic insulin resistance." (PMID 28351387, 2017). "Gene enrichment analysis revealed that SREBF1 is primarily involved in transcription regulation and nucleic acid metabolism and may also play a role in insulin resistance." (PMID 39953634, 2025). "High expression of SREBF1 may be a key for postpartum insulin supplementation to improve insulin resistance, significantly reduce NEFA concentrations, and prevent or treat ketosis and fatty liver in obese cows." (PMID 39881718, 2024). "The elevated expression of ADIPOQ in the CTL_NK group may explain their higher SREBF1 expression and improved insulin resistance." (PMID 39881718, 2024). "Conversely, the low expression of ADIPOQ in the INS_K group could contribute to their lower SREBF1 expression and more severe insulin resistance." (PMID 39881718, 2024). "Moreover, some studies reported DNA methylation profiles in several genes related to RXRA, SREBF1, PPARA, etc., closely associated with age-related susceptibility to hepatic insulin resistance and increased liver lipid metabolism." (PMID 37201099, 2023). "Similarly the upregulation of SREBF1 which is known to modulate insulin sensitivity is in line with the literature showing that radiation exposure can lead to insulin resistance." (PMID 33920039, 2021). "These markers located in ABCG1, PHOSPHO1, SOCS3, SREBF1, and TXNIP were associated with metabolic measures of insulin resistance including glucose concentration, BMI, waist-to-hip ratio, and homeostatic model assessment for insulin resistance (HOMA-IR)." (PMID 32211026, 2020). "SREBF1 is a transcription factor participates in lipogenesis, insulin resistance, and inflammatory response, which may contribute to the development of T2D." (PMID 32425817, 2020).
Insulin resistance (continued). "Metabolically, dwarfism protects from hepatic insulin resistance, reduces high-fat diet induced liver steatosis and suppresses de-novo lipogenesis genes including Elovl6, Acly and Fasn, thus indicating reduced lipogenic activity through Srebf1." (PMID 30462643, 2018). "Insulin resistance in turn may contribute to steatosis by inducing sterol regulatory element binding transcription factor 1 (SREBF1) that will lead to an increase in fatty acid biosynthesis." (PMID 27293514, 2016). "The genetic variability within the SREBF1 gene may play a role in insulin resistance or type 2 diabetes." (PMID 25270430, 2014). "The increased mRNA expression of SREBF1 induced by insulin supplementation in obese cows, is a critical factor for significantly upregulating lipogenic genes, and also a key target for improving insulin resistance and the significant reduction in NEFA in obese cows." (PMID 39881718, 2024). "Notably, the high expression of SREBF1 postpartum induced by insulin supplementation may serve as a key point to relieve insulin resistance, lower NEFA concentrations in obese cows." (PMID 39881718, 2024). "The DEGs Slc27a1, Cpt1a, Srebf1, and Foxo1 were enriched in insulin resistance pathway and also appeared in the network of top 10 upregulated and downregulated mRNAs, indicating these four mRNAs might play key roles in the development of hyperglycemia and T2D in GK rats at the age of 3 and 4 weeks." (PMID 32095365, 2020). "Reduced mRNA expression of AKT2, SREBF1 and GLUT4 in the subcutaneous adipose tissue, as well as the downregulation of SREBF1-regulated lipogenic genes, indicated insulin resistance occurred in early lactation cows." (PMID 39881718, 2024). "Key down-regulated genes (i.e., CREB5, SLC2A4, SREBF1, CYP1A1, CHARD and COMP) are related to insulin resistance, response to virus infection, AMPK signalling and ECM receptor interaction (Table A6)." (PMID 34830490, 2021). "Among these DMRs, SREBF1, HOXA5, CPT1A, LPIN1, and PHGDH have established roles in adipose tissue biology and insulin resistance." (PMID 33243154, 2020). "The transcription factor Srebf1 (SREBP1) is a key regulator of lipogenic enzyme expression in the liver and mediates hepatic insulin resistance through inhibition of IRS-2." (PMID 28351387, 2017). "Mice fed high fat western diet for one week demonstrate a robust increase in the expression of intestinal SREBF1 and SCD-1, and develop insulin resistance with little change in hepatic gene expression." (PMID 22073239, 2011). "However, the gene expression of AKT2, SREBF1, and GLUT4, and lipogenic genes regulated by insulin was significantly lower in the INS_K group, indicating that some cows have more severe insulin resistance that cannot be relieved by exogenous insulin supplementation." (PMID 39881718, 2024). "Ezetimibe administration may inhibit high fat-induced insulin resistance by reducing intestinal fat absorption and weight gain, rather than via downregulation of Srebf1 as suggested previously." (PMID 25310357, 2014). "On the other hand, the reduced SREBF1 expression could also decrease lipogenesis in smaller adipocytes and hinder adipocyte differentiation via PPARG down-regulation, leading to increased insulin resistance." (PMID 22471940, 2012).